TNF (tumor necrosis factor)
Diseases named in the same sentence as TNF in open-access papers (continued):
Sharing a sentence is not in itself a finding about the gene and the disease.
infection (continued). "In summary, for the first time it has been shown that CHIKV triggers robust TNF production (a key mediator of CHIKV induced inflammation) in the host macrophages via both p-p38 and p-JNK/p-c-jun pathways and viral protein nsP2 interacts with both the MAPKs during infection." (PMID 31031770, 2019). "Consequently, we analyzed the mRNA levels of the proinflammatory cytokines TNF-α, IL-1β, and IL-6 and the anti-inflammatory cytokine IL-10, as well as the antimicrobial peptides TAP, DEFB1, and BNBD5 in LEAS-pretreated bMECs before and after infection." (PMID 31612151, 2019). "Remarkably, at the end of week 8 after infection, Th1 responses were observed in the saline treated, as well as in the F1 and F3-vaccinated mice that exhibited increased IFN-γ/IL-10 ratios, and in the saline treated and F1-vaccinated mice, that showed elevated TNF-α/IL10 ratios." (PMID 31024556, 2019). "However, pre-infection of cells with S. pneumoniae does not inhibit the induction of Pro-IL-1β or TNFα by the TLR ligand LPS, thus ruling out priming as the target of S. pneumoniae-mediated inflammasome inhibition." (PMID 31375698, 2019). "TGF-β but no TNF or IL-1 was detected after ex vivo infection of swine macrophages and the responses to IFN-γ and LPS were suppressed in infected macrophages, indicating ASFV could suppress the immune response." (PMID 31725732, 2019). "TNF-α is not usually detectable in healthy individuals, but elevated serum and tissue levels are found in inflammatory conditions, and serum levels correlate with the severity of infections." (PMID 31816903, 2019). "Analysis of RNA-seq dataset from spleens of chickens four days after intranasal infection with bursal disease virus (IBDV) showed a significant induction of TNF and TNFR1 (p ≤ 0.05); no induction of TNFR2; and no or low expression of leptin and LEPR (<1 RPKM), respectively." (PMID 31514326, 2019). "Considerable evidence also links TNF to the pathology of PTB, including increased TNF concentrations in women in preterm labour and women with PPROM, as well as mechanistic roles for TNF in mediating membrane rupture, cervical ripening and infection-induced PTB25." (PMID 31043691, 2019). "Interestingly, in response to Mtb WCL stimulation, TNFα, IL6, IL12p40, and IL1β were produced to a significantly higher extent by BAL cells of cynomolgus macaques already prior to infection, concordant to the pro-inflammatory profile of circulating monocytes in cynomolgus macaques." (PMID 31736945, 2019). "NF-κB is activated through a wide range of stimuli such as TNF-α, IL-1β and LPS and acts as a central regulator of the IEC innate immune response and as an essential transcription factor for integrating the pro-inflammatory response to infection with enteroinvasive bacteria." (PMID 31035617, 2019). "The levels of cytokines in the supernatants of these cultures revealed a significant increase in TNF-α, IFN-γ, IL-10, and GM-CSF only in the control group after 24 h of L. amazonensis infection, with a gradual increase until 72 h post-infection, as compared to the IGHD subjects (p < 0.05)." (PMID 31544067, 2019). "Three days post-infection, the E. coli challenge significantly increased the expression of nuclear factor-κB (NF-κB), peroxisome proliferator-activated receptor-γ (PPAR-γ), toll-like receptor 4 (TLR4), IL-1β, and IL-6 (P < 0.05) and tended to increase the expression of TNF-α (P = 0.052)." (PMID 29948799, 2019). "Infection studies using this model demonstrated that ZIKV did not easily infect the HBMEC model, but that exposure to TNF-α could enhance infection." (PMID 31338335, 2019). "Infection with C. albicans, but not with C. parapsilosis, elicited strong proinflammatory responses, as measured by whole-fish cytokine expression and local activation of NF-κB signaling and TNF-α expression." (PMID 31088918, 2019).
infection (continued). "The pyrogenic cytokines (IL1 and TNFα) are the first to be secreted in response to pathogens, and their significantly high expression levels in porpoises living in the TZO suggest the stimulation of the acute phase of the immune response to stress and infection." (PMID 32116734, 2019). "The hepatic NK cells population and IFN-γproduction were decreased respectively at 2, 4, 12 weeks post E. multilocularis inoculation, but at 24th week after infection no change was observed, while TNF-α and granzyme B levels had no significance in designated time points." (PMID 31500589, 2019). "Infection with EV 71 can activate the c-Jun NH2-terminal kinase (JNK) and p38 mitogen-activated protein kinase (MAPK) signaling pathways, thereby contributing to increased viral replication and secretion of cytokines such as interleukin (IL)-2, IL-6, IL-10, and tumor necrosis factor (TNF)-α." (PMID 30545363, 2018). "However, the possibility of an interaction between UL26 and NFκB at early times during infection cannot be ruled out, as UL26-deficient virus is more sensitive to challenge with TNFα." (PMID 30134546, 2018). "In addition, we saw no changes in tumor necrosis factor (TNF-α), IL-8, CXC chemokine ligand 2 (CXCL2), or IL-10 signaling in MRP1 knockdown cells either before or after infection as measured by an enzyme-linked immunosorbent assay (ELISA)." (PMID 29976647, 2018). "Accordingly, we propose that DMARDs introduction (but not TNF inhibitors) in RA patients makes them better regarding infections, this supports again the possibility that something about the immunology of the disease and the pre-disease states are driving the infection risk." (PMID 30555464, 2018). "In the context of a bacterial infection that elicits a rapid, robust, or sustained inflammatory TNF response and an attenuated or absent anti‐inflammatory response, there is enhanced clearance of infection; however, there is also enhanced cellular apoptosis and septic shock." (PMID 30426723, 2018). "Twenty-four hours after infection, we assessed inflammatory responses of the macrophages by measuring the levels of cytokines, including granulocyte/macrophage colony-stimulating factor (GM-CSF), IFN-γ, interleukin (IL)-2, IL-4, IL-6, IL-8, IL-10 and TNF-α, secreted in the culture supernatant." (PMID 29712918, 2018). "Four weeks post-infection, a real-time PCR analysis of inflammatory gene expression revealed that purified macrophages from infected WT mice exhibited enhanced IL-10, Arg-1, MCP-1, RELMa, and IL-6 but reduced TNF-α, IL-12, and iNOS mRNA levels, which exhibited an M2 dominant- polarized phenotype." (PMID 30589840, 2018). "This suggests that the source of TNFα seen by Parkunan may not be from cells in the retina at this stage of infection, but rather from infiltrating neutrophils, given that cytokine assays were performed on homogenized whole globes." (PMID 29661181, 2018). "Compared to those of mock infection or VR2332c, JA142c and poly I:C induced significantly increased transcript levels of IFN-β and pro-inflammatory cytokines (IL-1α, IL-1β, IL-6, IL-8, IL-12, and TNF-α) at either two or all three time points assayed (12, 24 and 36 hpi)." (PMID 30509265, 2018). "Additionally, TNF-dependent mechanisms of protection appear localized to the site of infection, as we observe no significant systemic changes in TNF during heterologous rechallenge but do observe induction in splenic macrophages and memory T cells." (PMID 29438281, 2018). "The lack of immediate increase in both IL6 and TNF following miR-122 inhibitor infection shows that these cytokines possibly are not among direct targets of miR-122 and miR-122 inhibition increases these cytokines through indirect effect on some other elements of hepatic signal transduction." (PMID 30024933, 2018).
infection (continued). "Hence, increased production of PGE2 in macrophages that had contact with EV Y supports reduced production of pro-inflammatory cytokines (TNF-α) and NO that occurred in plasma and spleen-cell supernatants (TNF-α and IL-6) from mice inoculated with EV Y before infection." (PMID 29755471, 2018). "Regardless of the infection, TNF-α, IL-15, IL-18, and CCL-5 were absent or barely detected." (PMID 30420629, 2018). "The proportion of CD4 T cells secreting TNF-α or IFN-γ and CD8 T cells producing IFN-γ were further elevated in infected IL-10 KO splenocytes (p < 0.001), indicating that expression of IL-10 during naive T cell priming upon infection suppresses the generation of T cell responses." (PMID 30233599, 2018). "Notably, infection of C. glabrata, unlike that of S. cerevisiae and C. albicans, is known to induce reduced production of IL-6, IL-8, TNFα, IL-1β, and IFN-γ in human monocyte-derived macrophages." (PMID 29491142, 2018). "However, SeV85AB boosting resulted in a response to infection that contained a higher percentage of Ag85AB-specific poly-functional lung T cells, notably CD4+ T cells with the phenotypes IL-2+TNF-α+/IL-2+, and CD8+ T cells of phenotypes IFN-γ+IL-2+TNF-α+/IL-2+." (PMID 30123219, 2018). "Focusing on the modulation of immune responses by EVs in the acute phase of infection, only after stimulation with EVs from YuYu (DTU TcI) and CL-14 (DTU TcVI), peritoneal macrophages from C57BL/6 mice produced high levels of proinflammatory cytokines (TNF-alpha) and NO, via the TLR-2." (PMID 29727453, 2018). "Infection of MDMs with MERS-CoV appreciably induced the secretion of antiviral cytokines (IFN-α2, IFN-γ, and IL-12p40), moderately or appreciably up-regulated proinflammatory cytokines (TNF-α, IL-6), and variably upregulated inflammatory chemokines (MIP-1α, IP-10, RANTES, IL-8)." (PMID 29566060, 2018). "All together these results suggest that both the immunization (iC+CT) and the infection (LC) induce a similar INF-γ/ IL-17 response; however, the higher expression of TNFα induced by the infection suggest that this cytokine could be implicated in tissue damage." (PMID 29946313, 2018). "TNF-α expression also increased after infection with cercariae (infected no-treatment control)." (PMID 29703259, 2018). "It has been shown that EVs produced by macrophages infected for 3 days with S. Typhimurium and Mycobacterium bovis provoke an increase in TNF-α production in uninfected macrophages, but other cytokines or earlier time points of infection were not tested for S. Typhimurium." (PMID 29158431, 2018). "The hepatic levels of TNF, IL-6, IL-1β, and IL-12p70 did not change significantly upon infection." (PMID 29568732, 2018). "The fact that CD18 neutralizing antibody was not as efficient in blocking PMN adhesion to TNF-α treated BECs could be due to the excess level of ICAM-1 upregulated by TNF-α as compared to PUUV infection." (PMID 30283445, 2018). "To further test if cytokine production in response to infection was proportional to intracellular TG levels, we differentiated DGAT1 shRNA and control shRNA expressing THP1 cells with NcS and then sought to measure release and expression of TNFα in response to Mtb infection." (PMID 30018616, 2018). "Examination of the gingivae for pro and anti-inflammatory cytokine expression 4 days post infection revealed that treatment with RvD2 maintained tissue homeostasis by preventing increased expression of the pro-inflammatory cytokines, such as IFN-γ, IL-1β, and TNF-α and decreased expression of IL-10." (PMID 29922275, 2018). "However, on day 46-post infection, the absolute numbers of both antigen-specific CD8+ T cells were significantly decreased and this was accompanied by a marked decrease in the frequencies and absolute numbers of IFN-γ and TNF-α producing cells." (PMID 29672594, 2018).
infection (continued). "Against this, we observe an expansion of Ag85-specific CD4+ T cells with infection, alterations on the T cell activation profile that are more exuberant in the transgenic over the non-transgenic cells and more IFNγ+ and TNF+ CD4+ T cells in the transgenic compartment." (PMID 29499041, 2018). "However, the RH group had lower TNF-α levels than the ME49 group at day 3, 5, and 9 post-infection." (PMID 30564216, 2018). "While we observe a loss of protection at day 3 post-infection during secondary challenge in the absence of TNF, the levels of bacteria are similar to those of a normal primary infection, indicating an altered mechanism of action during a secondary infection compared to a primary infection." (PMID 29438281, 2018). "At 3 dpi, the levels of IFN-γ, IL-6, IL-10, MCP-1, and TNF-α in BALB/c mice infected with MA/12 were considerably higher than in animals inoculated with PH/13 or BR/08; however, only the IL-10 elevation was significant (P < 0.05) relative to that observed with PH/13 infection." (PMID 28779075, 2017). "In the CNS, TNF is produced by immune and non-immune cells; however, the mechanisms by which cell-specific TNF acts to control CNS-TB and cellular recruitment to the infection site are not clearly defined." (PMID 28280495, 2017). "Our in vitro assay showed that splenic CD11b+ cells from PbANKA-infected mice at days 0, 3, and 5 post-infection co-cultured with Pb-iRBC had higher TNF-α production in the supernatant compared to that co-cultured with uRBC, and anti-Tim-3 antibody treatment further promoted TNF-α production." (PMID 28824565, 2017). "In addition, our transcriptional profiling identified a functional difference between well-documented cytokines and chemokines between elite controllers and rapid progressors during early infection; there was a significant co-expression of MCP1, TNF and IL10 only in elite controllers." (PMID 28350860, 2017). "Unlike TNFα, IL-6 is critical to resistance against M. tuberculosis, but it is dispensable for the control of mycobacterial growth after low-dose aerosol-delivered infection." (PMID 28223969, 2017). "Considering that miR-130a-3p, miR-146a, miR-181a, miR-181b, miR-301a-3p, and miR-351-5p might participate in the negative regulation of TNF-α production in Omp25-expressing cells, we measured the expression of these miRNAs in PAMs and mouse RAW264.7 cells after LV-Omp25 infection." (PMID 29387067, 2017). "Therefore, during infection, exogenous TNF-α induces cell death in the absence of SseK-mediated inhibition." (PMID 28069818, 2017). "In accordance with this, glycolytic lactate production was strongly enhanced, pointing to an upregulation of aerobic glycolysis, which could also be mimicked with TNF-α and AA treatment in the absence of infection." (PMID 28634388, 2017). "Additionally, the IDR (p < 0.0001, R = −0.7815) and the frequencies of multifunctional CD4+ (p < 0.0500, R = −0.2803) and CD8+ T cells (p < 0.0001, R = −0.7837) expressing IL-2, TNF-α, and IFN-γ, after infection, were strong correlates of prophylactic efficacy." (PMID 28280494, 2017). "In contrast to the lack of seizure control observed with XPro1595 treatment, results in the genetically modified mice strains suggest that TNFα signaling through the TNFR1 pathway could indeed be a prominent mechanism through which hyperexcitability and seizure activity occur after TMEV infection." (PMID 28497109, 2017). "In fact, TNF-α acts synergistically with IFN-γ to stimulate the production of nitric oxide (NO) by macrophages and influences the expression of chemokines, such as CCL5, CCL9, CXCL10, and CCL2, which induce migration to and maintenance of immune cells in the infection site." (PMID 28659665, 2017).
infection (continued). "As in the case for TNF requirement that needs to be at the right time with sufficient levels to be efficient, MDSC can also exert protective activity during a specific time of the infection to prevent overt inflammation whereas they can be deleterious during chronicity." (PMID 28890718, 2017). "Only gut epithelial cells specifically reacted to NMI infection with a significant upregulation of IL-1β, lung epithelial cells with a specific downregulation of IL-6 whereas infection with NMII resulted in a distinct up-regulation of TNF-α in lung epithelial cells." (PMID 28403908, 2017). "Interestingly, the high level of TNF-α in control-CM was not increased by H37Rv infection, while a significant reduction in M-CM was detected." (PMID 28852268, 2017). "However, TNF‐α:IL‐10 ratios in individual serum samples were significantly lower in HFD compared to ND mice at 8 weeks post‐infection, primarily due to reduced levels of TNF‐α, and not increased IL‐10 abundance." (PMID 27794208, 2017). "A possible explanation is that colostral TNFα induced an increase of MHC class II expression on antigen presenting cells and expression of receptors that facilitate transcytosis of SIgA into exocrine fluids in the respiratory and gastrointestinal tracts to counteract infection." (PMID 29109718, 2017). "All TNF−/− mice died within 5 days, and 80% of mice with etanercept treatment died by day 6, as expected; by contrast, mice vaccinated with TNFKi did not die due to infection during this period." (PMID 29184553, 2017). "As for serum cytokines, cytokine production by macrophages from infected HFD mice at both 1 and 8 weeks post‐infection was significantly less pro‐inflammatory than cytokine production by macrophages from infected ND mice, due to reduced TNF‐α production, but not increased IL‐10 secretion." (PMID 27794208, 2017). "The plasma TNF was elevated at 60 days of infection in mice treated or not with carvedilol." (PMID 28377930, 2017). "To investigate whether TNFα differentially impacts apoptosis of FL-high and DVG-high cells, we quantified the percentage of active caspase-3 positive cells among each sub-population during infection in the presence of neutralizing antibodies." (PMID 28986577, 2017). "Thus, infection appears to be important for inducing PmpG-Tet+ CD4+ T cells that can produce multiple cytokines; IFN-γ, TNF-α, and IL-17 which may only marginally aid in protection from bacterial load in the GT and reproductive tract inflammation." (PMID 28106821, 2017). "In anti-TNFα-treated animals, ampicillin or ciprofloxacin could prevent the escalation of the infection, which in the absence of antibiotic treatment would ultimately reach lethal bacterial numbers in the organs." (PMID 28087648, 2017). "This suggests that CD4+ T cells are not a main source of TNF-α during APP infection." (PMID 28166835, 2017). "Before starting anti-TNF therapy in endemic areas, clinicians should consider serological tests (IgG and IgM) and a chest radiograph to establish baseline, even if usually the infection is not the result of a reactivation." (PMID 28146077, 2017). "Recognition by TLRs induced antiparasitic activity and the production of pro-inflammatory cytokines, such as IL-1, IL-6, TNF, IL-12 e IFN-γ, which also could influence the rate of NOS2/ARG1 during infection." (PMID 29379478, 2017). "We observed that the production of pro-inflammation TNF-α and IL-6 and the immunoregulatory IFN-β, MCP-1 and KC were significantly decreased later in infection (at 6 or 8 dpi) compared with non-treated mice, indicating the accelerated recovery from the immunity situation resulting from infection." (PMID 28235408, 2017). "However, TNF levels were significantly reduced at both 24 and 48 hours post-infection in the absence of Ly6Chi monocytes." (PMID 28384349, 2017).